BMP7 (bone morphogenetic protein 7)
Diseases named in the same sentence as BMP7 in open-access papers (continued):
Sharing a sentence is not in itself a finding about the gene and the disease.
colitis (5 papers, 2008 to 2023). Inflammation of the colon. "Compared with the control group, the decrease in body weight was 13.39% in the colitis group and 9.4% and 5.5% in the Dex and BMP7 groups, respectively." (PMID 37626658, 2023). "In this review, we concluded that anti-BMP6 reagents, exogenous BMP7 and FST all have impacts on decreasing IBD-associated pro-inflammatory cytokines, especially IL-6 which attenuates DSS-induced mice colitis." (PMID 37391444, 2023). "The colon weight/length ratio, which is a marker of colonic damage and tissue edema, was significantly higher in the colitis group compared with the control, Dex, and BMP7 groups." (PMID 37626658, 2023). "Treatment with Dex decreased its expression to the level of healthy controls, and treatment with BMP7 suppressed it even more, which was consistent with our previous work that indicated a strong anti-inflammatory effect of BMP7 in colitis." (PMID 37626658, 2023). "Several studies have supplied supporting evidence to the current findings indicating an upregulation of BMPR2 expression at 2 days following BMP-7 administration in various models including TNBS-induced colitis." (PMID 24376781, 2013). "N. was observed in the BMP7-treated rats compared with the colitis group." (PMID 37626658, 2023). "Also, the microscopic score was significantly increased in the colitis, Dex, BMP7, and EtOH groups compared with the control group." (PMID 37626658, 2023). "However, experiments with rat models of colitis demonstrated the prominence of exogenous BMP7 in lowering pro-inflammatory cytokine production (especially IL-6) and thus protecting mucosa." (PMID 37391444, 2023). "Furthermore, it was decreased in the group treated with Dex and BMP7 compared with the colitis group (p = 0.024 and p = 0.04, respectively)." (PMID 37626658, 2023). "Interestingly, a significant increase was noted in the Dex and BMP7 groups compared with the colitis group." (PMID 37626658, 2023). "Hence, we concluded that the resolution of colitis was positively affected by treatment with both Dex and BMP7." (PMID 37626658, 2023). "Both colitis with and without Dex and BMP7 treatments caused no changes in morphometric parameters of cortical bone." (PMID 37626658, 2023). "Previous studies have revealed that although BMP7 has anti-inflammatory effects, its levels significantly decrease in the acute phase of TNBS-induced colitis." (PMID 37391444, 2023). "According to our results, the administration of both Dex and BMP7 increased the expression of OPG in the colon, while its expression in the colitis group decreased." (PMID 37626658, 2023). "A prior work on zebrafish utilising TNBS-induced mice found increased expression of BMP7 in the acute phase and BMP6 in the chronic phase of colitis." (PMID 36500396, 2022). "An increase was also visible in the colitis and BMP7 groups, but not compared with the control group." (PMID 37626658, 2023). "As a result of the BMP7 treatment, morphometric parameters of trabecular bone increased, and increased trabecular separation noted in the colitis group did not appear." (PMID 37626658, 2023). "Due to a significant decrease in the number of trabeculae, an increase in trabecular separation was observed in the colitis group, whereas this was not seen in the Dex and BMP7 groups compared with the control group." (PMID 37626658, 2023). "To investigate whether the BMP7 treatment affected the resolution of colitis, we used a TNBS-induced experimental model of colitis." (PMID 37626658, 2023). "Treatment with both Dex and BMP7 initiated a trend toward normalization of TGF-β expression, which was changed upon TNBS-colitis establishment, in line with our earlier study highlighting the important role of BMP7 in maintaining normal TGF-β expression in colitis." (PMID 37626658, 2023).
hypospadias (5 papers, 2016 to 2023). Hypospadias is the displacement of the urethral meatus on the ventrum of the penis. "GWAS for developmental defects of the male reproductive system have also identified candidate genes for hormonal (AR, steroidogenesis, ESR1, and ESR2) and nonhormonal (FGF8, FGFR2, BMP4, and BMP7) pathways underlying hypospadias." (PMID 26662846, 2016). "Mutation of BMP4 and BMP7—two factors that play a role in normal urethra development, along with HOXA4 and HOXB6, were identified in Chinese patients with hypospadias, but without a clear association." (PMID 37238140, 2023).
inflammatory bowel disease (5 papers, 2008 to 2025). A spectrum of small and large bowel inflammatory diseases of unknown etiology. "In addition, BMP7 administration conferred intestinal mucosal protection and reduced systemic IL-6 expression levels in an inflammatory bowel disease model." (PMID 25132736, 2014).
knee osteoarthritis (5 papers, 2010 to 2024). "A phase I study evaluating the safety and tolerability of BMP-7 in patients with symptomatic knee osteoarthritis reported promising results." (PMID 39598266, 2024). "The double-blind, randomized, single dose incremental safety study of bone morphogenetic protein (38A BMP-7) in knee OA subjects (NCT01133613) and the dose discovery study of BMP-7 in knee osteoarthritis patients (NCT01111045) are also being further evaluated." (PMID 37089415, 2023). "A phase 1 safety and tolerability study of BMP-7 in symptomatic knee osteoarthritis was conducted in 2010 and demonstrated that there was no dose-limiting toxicity identified." (PMID 36902773, 2023).
microphthalmia (5 papers, 2012 to 2019). Congenital or developmental anomaly in which the eyeballs are abnormally small. "BMP7 gene targeting experiments in the mouse lead to a variable phenotype that ranges from mild microphthalmia to anopthalmia." (PMID 22761776, 2012). "First, Bmp7 null mice display microphthalmia and optic fissure defects, similar to sox11 null mice." (PMID 25010521, 2014).
neuroblastoma (5 papers, 2010 to 2026). Neuroblastoma (NB) is the most common solid, extracranial childhood tumor. "Higher BMP7 expression was associated with the shorted event free survival and overall survival of neuroblastoma." (PMID 41632777, 2026). "However, only BMP7 was associated with the prognosis of neuroblastoma in all six neuroblastoma cohorts." (PMID 41632777, 2026). "The expressions of BMP7 were higher in neuroblastoma patients with MYCN amplification or age ≥ 18months or in stage 4 neuroblastoma." (PMID 41632777, 2026). "Moreover, higher BMP7 was associated with the shorted event free survival and overall survival of MYCN amplified or stage 4 neuroblastoma." (PMID 41632777, 2026). "9cRA enhances production of glial cell line derived neurotrophic factor (GDNF), and bone morphogenetic protein-7 (BMP-7) protein, in human neuroblastoma cells and U2 OS cells, respectively." (PMID 23040108, 2012). "The prognosis of BMP7 in neuroblastoma was independent of age and MYCN amplification." (PMID 41632777, 2026).
type 2 diabetes (5 papers, 2014 to 2023). "In our study, we found that two SNPs in BMP7 gene may be susceptibility variants of DN in Han Chinese patients with type 2 diabetes." (PMID 25359423, 2014). "It has been discovered that BMP7, one of the gene ontology annotations in GO kidney mesenchyme development, could augment insulin sensitivity in mice with type 2 diabetes by potentiating PI3K/AKT pathway." (PMID 31407623, 2019). "Using pharmacophore target analysis in a network pharmacology approach, we identified five potential target genes for celastrol in the treatment of type 2 diabetes, including RBP3, BMP7, S100A11, HBB and IQUB." (PMID 36339449, 2022).
acute myocardial infarction (4 papers, 2018 to 2022). Necrosis of the myocardium, as a result of interruption of the blood supply to the area. "The gene variants of BMP7 stimulate inflammation and are associated with acute myocardial infarction and AD." (PMID 35681440, 2022). "BMP7 is involved in Axon guidance and in the recovery of cardiac function after myocardial infarction." (PMID 35681440, 2022). "A recent study showed that another member of BMP family, BMP-7, facilitates the recovery of cardiac function after acute myocardial infarction through attenuating TGF-β1 (transforming growth factor-β1) and its downstream signaling pathway Smad2/355." (PMID 30082698, 2018). "In this study, the group established acute myocardial infarction by ligating the left anterior descending artery with and without BMP-7 treatment." (PMID 31979268, 2020).
Arthritis (4 papers, 2015 to 2016). Inflammation of a joint. "In our study, BMP2 and BMP7 were downregulated within the arthritic paw, which is similar to findings in the collagen-induced arthritis model." (PMID 26801240, 2016). "The increased expression and production of specific BMPs (i.e., BMP2, BMP6, and BMP7) in the synovium and synovial fluid of patients with RA as well as in mouse models of arthritis have been reported by different groups." (PMID 26215036, 2015). "Several BMP ligands, including BMP2, BMP6, and BMP7, have been shown to be upregulated in the synovium of patients with RA as well as in tumor necrosis factor-alpha (TNF-α) transgenic mice developing arthritis and in collagen-induced arthritis models." (PMID 26215036, 2015). "For example, the bone morphogenetic protein 7 (BMP-7), also known as osteogenic protein 1 (OP-1), is a growth factor that stimulates cartilage and bone formation during embryonic development and postnatal growth, and has shown good promise in preclinical models of arthritis." (PMID 25561745, 2015). "The expression of bone morphogenetic protein 2 (BMP2) and BMP7, which may act as osteoblast growth factors, was not increased in DTHA compared with paws of untreated naive mice, but it seemed to decrease upon arthritis induction." (PMID 26801240, 2016).
Insulin resistance (4 papers, 2022 to 2025). Increased resistance towards insulin, that is, diminished effectiveness of insulin in reducing blood glucose levels. "In diabetic mice and palmitate (PA)-induced insulin-resistant HepG2 and AML12 cells, BMP7 can inhibit the active of MAPKs to regulate insulin resistance." (PMID 35231067, 2022).
lymph node metastasis (4 papers, 2011 to 2021). "We also found a significant association between patients with lymph node metastasis and overexpression of BMP7 (47.4%, P=0.005), CALD1 (42.1%, P=0.020), CDH1 (52.6%, P=0.001), COL3A1 (42.1%, P=0.020), EGFR (47.4%, P=0.005), ERBB3 (57.9%, P=0.000), PLEK2 (47.4%, P=0.024), and TCF4 (52.6%, P=0.001)." (PMID 34527572, 2021). "Univariate analysis showed that tumour histology, the depth of invasion, tumour size, lymph node metastasis, lymphatic invasion, venous invasion and BMP-7 expression were significantly related to postoperative survival (P<0.01)." (PMID 21224856, 2011).
lymphoma (4 papers, 2012 to 2024). A malignant (clonal) proliferation of B- lymphocytes or T- lymphocytes which involves the lymph nodes, bone marrow and/or extranodal sites. "We checked the expression of known BMP ligands for ACVR1 and found that only BMP6 and BMP7 are expressed at high levels in lymphoma samples in CCLE and TCGA." (PMID 38229201, 2024). "BMP6 and BMP7 are upregulated by PRC2 inhibition or depletion in lymphoma cells and we purchased and applied them individually." (PMID 38229201, 2024). "The BMP7-promoter methylation status was analyzed by qMSP in 37 lymphoma samples and CD19+ B-cells from 10 healthy donors." (PMID 25226156, 2014). "In this study, lymphoma cell lines as well as malignant B cells from lymphoma patients were resistant to BMP-7." (PMID 23049692, 2012). "Combined with expression of BMP7 in both normal and malignant B cells, this suggests that lymphoma cells can escape autocrine growth-inhibitory effects of BMP-7." (PMID 23049692, 2012). "Studies in lymphoma cell lines of different subtypes showed that seven out of ten expressed BMP7, whereas three out of ten had detectable BMP6 levels." (PMID 23049692, 2012). "Expression of BMP7 in lymphoma cell lines was further confirmed at the protein level, but did not correlate well with mRNA levels." (PMID 23049692, 2012). "Moreover, induced expression or application of BMP7 in lymphoma cells results in decreased proliferation." (PMID 38229201, 2024). "Furthermore, high levels of BMP6 and BMP7, along with ACVR1, are associated with longer survival in lymphoma patients, underscoring the clinical relevance of this study." (PMID 38229201, 2024). "Taken together, we identified several genes (BMPER, BMP7, CDH1, DUSP4 and LRP12) which were frequently methylated in major lymphoma types." (PMID 25226156, 2014). "Through the differentially expressed genes (DEG) and GO analysis using RNA‐seq data from WSU‐DLCL2 lymphoma cell carrying EZH2Y641F, we observed an enrichment of TGF‐beta pathway with PRC2 inhibitor treatment, with BMP7 and ACVR1 as the top DEGs and multiple BMP ligands upregulated." (PMID 38229201, 2024). "The genes BMP6, BMP7 and ACVR1 are directly repressed by PRC2 in lymphoma cells." (PMID 38229201, 2024). "In addition, BMP7, which is methylated in 23% of the analyzed patients, as well as BMP6, which previously has been reported to be frequently methylated in lymphoma, are members of the TGF-β superfamily of cytokines." (PMID 25226156, 2014). "In this study, we did not identify genes that were methylated in a lymphoma type or subtype specific pattern in patient samples, although the BMP7 gene promoter was methylated in DLDCL ABC and not DLBCL GCB cell lines." (PMID 25226156, 2014). "However, to the best of our knowledge, this is the first time BMPER, BMP7, DUSP4 and LRP12 are reported to be methylated in lymphoma." (PMID 25226156, 2014). "The relationship between BMP-7 and survival of lymphoma patients has not been studied, but expression of BMP6 has previously been associated with prognosis in patients with hematological malignancies." (PMID 23049692, 2012). "This could probably explain why BMP7 was not detectable in the majority of lymphoma cells from patients with primary resistant MCL (before treatment and at the time of progression)." (PMID 24069261, 2013). "We have previously shown that BMP-7 potently induced apoptosis in normal B cells, which was in contrast to no or little inhibitory effect of this BMP in the lymphoma cells tested." (PMID 23049692, 2012).
myeloma (4 papers, 2017 to 2024). "BMP-7 has been shown to induce apoptosis in naïve and memory B cells from peripheral blood, as well as in myeloma cell lines and myeloma cells from patients." (PMID 28489883, 2017).
ovarian tumor (4 papers, 2010 to 2024). "Taken together, the data of this study suggests that BMP7 is important in metastasis and ovarian tumour progression, however the effect on biological mechanisms need to be investigated further both in vitro and in vivo." (PMID 37688374, 2023). "In the light of findings indicating an inverse relationship between EMT and NED in panNET and non-pancreatic tumors, we sought to reveal how the EMT inducers TGF-β1 and BMP-7 would affect EMT and NED in PDAC and in SCCOHT, a rare ovarian tumor." (PMID 39682758, 2024).
Parkinson disease (4 papers, 2012 to 2025). A progressive degenerative disorder of the central nervous system characterized by loss of dopamine producing neurons in the substantia nigra and the presence of Lewy bodies in the substantia nigra and locus coeruleus. "Since 9cRA enhances BMP7 expression, we reasoned it may also induce protection against 6-OHDA lesioning in an animal model of Parkinson’s disease (PD) through the BMP7 pathway." (PMID 23040108, 2012).
rheumatoid arthritis (4 papers, 2006 to 2020). A chronic, systemic autoimmune disorder characterized by inflammation in the synovial membranes and articular surfaces. "BMP-7 was mainly localized in the cartilage layer, but was also detected in the synovial knee fluid of patients with OA and rheumatoid arthritis (RA)." (PMID 20670444, 2010). "In patients with rheumatoid arthritis, stimulation with IL-1β induced BMP-2 and BMP-6, but not BMP-4, BMP-5, or BMP-7 in fibroblast-like synoviocytes." (PMID 32290085, 2020).
sarcopenia (4 papers, 2022 to 2025). Progressive decline in muscle mass due to aging which results in decreased functional capacity of muscles. "This is indicative of BMP‐7 being a potential therapeutic intervention that can be administered to attenuate weight loss and sarcopenia exhibited after ponatinib treatment." (PMID 36945866, 2023). "Moreover, significant decrease in loss of body weight and sarcopenia, improved muscle function and decrease in muscle atrophy and fibrosis after BMP‐7 treatment was observed." (PMID 36945866, 2023). "Evident attenuation of apoptosis, sarcopenia, muscle dysfunction, atrophy, and adverse muscle remodeling after BMP‐7 treatment is promising." (PMID 36945866, 2023). "Evident amelioration of metabolic gene expression, increased inflammation and pyroptosis, increased pathological cell signaling, sarcopenia, and decreased muscle function data show that treatment with BMP-7 is promising." (PMID 36829889, 2023). "Overall, we provide evidence that ponatinib‐induces apoptosis leading to sarcopenia and muscle myopathy with decreased function which was attenuated by BMP‐7." (PMID 36945866, 2023). "The finding of the present study that BMP-7 can reduce systemic hyperlipidemia, infiltration of monocytes, inflammation, and pyroptosis leading to a decrease in sarcopenia, fibrosis, atrophy, and muscle dysfunction in diabetic muscle myopathy is novel." (PMID 36829889, 2023). "Interestingly, the present study data show that BMP-7 treatment significantly reduces hyperlipidemia-induced pyroptosis-associated muscle atrophy and sarcopenia, while improving diabetic muscle dysfunction, indicating BMP-7 could serve as a future therapeutic agent to treat diabetic muscle myopathy." (PMID 36829889, 2023). "Research by Narasimhulu and Singla demonstrated that Bone Morphogenetic Protein-7 (BMP-7) alleviates diabetic myopathy by attenuating lipid accumulation and inflammation, which subsequently suppresses pyroptosis and mitigates sarcopenia and adverse muscle remodeling." (PMID 41334559, 2025). "Finally, our data determined the preventive effects of BMP-7, an osteogenic protein, on hyperlipidemia-induced inflammation, cellular mechanisms, sarcopenia, fibrosis, and muscle dysfunction." (PMID 36829889, 2023). "A significant improvement in sarcopenia was observed upon BMP-7 treatment (p < 0.05)." (PMID 36829889, 2023). "Interventional treatment with BMP-7 attenuates hypercholesterolemia-induced inflammation-mediated sarcopenia and adverse muscle remodeling, suggesting BMP-7 could be a potential treatment option for diabetic muscle myopathy." (PMID 36829889, 2023).
tendinopathy (4 papers, 2013 to 2016). "Gene and protein expression of TGF-β and protein expression of BMP2, BMP4 and BMP7 were increased in the six studies that compared tendinopathy and healthy tendon tissues from the patella or the Achilles." (PMID 27863509, 2016). "Ectopic expression of BMP-2, BMP-4 and BMP-7 was observed in clinical samples of tendinopathy and collagenase-induced (CI) tendon injury rat model." (PMID 23964681, 2013). "There was ectopic expression of BMP-2, BMP-4 and BMP-7 in clinical samples of tendinopathy and collagenase-induced tendon injury rat model." (PMID 23964681, 2013). "BMP-2, BMP-7 and CTGF mRNA remained unchanged with tendon disease." (PMID 26883016, 2016).
type 1 diabetes (4 papers, 2014 to 2023). "In the early formation of type I diabetes in rats, the expression of renal BMP7 and its receptors was reduced or lost." (PMID 37365530, 2023).